CGAS (cyclic GMP-AMP synthase)
Diseases named in the same sentence as CGAS in open-access papers (continued):
Sharing a sentence is not in itself a finding about the gene and the disease.
tumor (continued). "On one hand, activation of cGAS–STING enhances antitumor immunity by facilitating immune cell infiltration and tumor clearance; on the other hand, excessive or chronic activation may drive tumor-promoting inflammation and immune evasion." (PMID 41415288, 2025). "Rupture of the micronuclei’s nuclear envelope has shown to trigger cGAS recruitment, and it has been proposed as a critical mechanism of surveillance in the context of chromosomally instable (CIN) tumours." (PMID 39984755, 2025). "Additionally, MnSx activated the cyclic guanosine monophosphate–adenosine monophosphate synthase (cGAS)–stimulator of interferon genes (STING) pathway, further enhancing the cellular autophagic response and accelerating tumor cell death." (PMID 39936146, 2025). "Additionally, the DNA component stimulates the cyclic GMP‐AMP synthase‐stimulator of interferon genes (cGAS‐STING) pathway, which synergizes with Dox‐induced immunogenic cell death (ICD) to promote a robust anti‐tumor immune response." (PMID 40052211, 2025). "The cGAS-STING pathway, a critical innate immune response mechanism, can be hijacked by tumors to evade immune detection by suppressing the activation of immune signaling, thus enabling cancer cells to escape immune surveillance and promote tumor progression." (PMID 40739089, 2025). "Consequently, PCK1 inhibits GTP-dependent cGAS activation and subsequent STING-promoted immune cell infiltration and activation in the tumor microenvironment, thereby promoting tumor growth in mice." (PMID 40567603, 2025). "Tumor treatment strategies based on the cGAS-STING pathway are gradually being developed, and increasing evidence shows that cGAS-STING agonists can effectively eliminate tumors and induce durable anti-tumor immune responses when combined with immunotherapy." (PMID 40006729, 2025). "Furthermore, cisplatin-induced DNA damage in tumor cells 4 generates double-stranded DNA (dsDNA) fragments, which trigger the release of CCL5 and CXCL10 via activation of the cGAS-STING signaling pathway." (PMID 39757995, 2025). "By leveraging nanotechnology to deliver cGAS‐STING agonists and augmenting the innate immune response, this method complements the action of genetically modified CAR‐T cells, which are engineered to precisely target and eradicate tumor cells." (PMID 41476652, 2025). "As a protective mechanism, tumor cells exposed to radiation can initiate negative feedback mechanisms that limit the sustained activity of the cGAS–STING pathway, potentially reducing its effectiveness in the anti-tumor immune response." (PMID 40355720, 2025). "The cyclic GMP-AMP synthase-stimulator of interferon genes (cGAS-STING) axis, an essential signaling pathway in innate immunity, is a DNA-sensing pathway that has been central to our understanding of intrinsic anti-tumour immunology in recent years." (PMID 40918140, 2025). "Upon tumor cell internalization, Mn2+ ions potentiated the binding of the stimulator of interferon genes (STING) to radiotherapy-induced double-stranded DNA (dsDNA), while 2′,3′-cGAMP acted as a secondary messenger to amplify cGAS-STING pathway activation." (PMID 40429976, 2025). "Therefore, the cGAS‐STING pathway becomes a critical immunological interface linking innate and adaptive responses, particularly in the context of tumor immunotherapy." (PMID 40672434, 2025). "Further studies have shown that cGAS in the mitochondria of tumor cells, such as Hep3B and PLC cells, could resist ferroptosis in tumor cells." (PMID 40959280, 2025). "In addition to RocA and powdery mildew alkaloids, manganese ions (Mn2+) have been found to be important cofactors of the cGAS-STING pathway, which can enhance anti-tumor immune responses and improve the efficacy of clinical immunotherapy." (PMID 40166469, 2025). "Overexpression of HDAC3 may facilitate tumor cell apoptosis and promote the release of factors such as IL-2 and IFN-γ by activating the CGAS-STING pathway." (PMID 40006729, 2025).
tumor (continued). "Our results demonstrated that EFTUD2 shaped the tumor immune microenvironment (TIME) and is closely related to genes involved in N6-methyladenosine (m6A) modification and the cyclic GMP-AMP synthase-stimulator of interferon genes (cGAS-STING) pathway." (PMID 40236649, 2025). "The expression of pTBK1 and pIRF3 in tumor tissues was dramatically upregulated in EB@MPCM based groups, because EB facilitated MPCM to accumulate at tumor site and form Mn2+ reservoir, leading to effective activation of cGAS‐STING pathway." (PMID 39792614, 2025). "Neither ADU-S100 or Poly I:C, lacking any distracting viral immunogens and both clinically relevant antiviral immune adjuvants triggering the STING/cGAS and TLR3 signaling cascade, respectively, were unable to prime OT-I responses at low-doses despite improved CD8 T cell infiltration into the tumor." (PMID 40166032, 2025). "The cGAS-STING pathway exerts anti-tumor effects through two different mechanisms: autonomous and non-autonomous." (PMID 41226461, 2025). "Additionally, DNA repair deficiencies lead to cytosolic DNA fragments, which activate the cGAS/STING pathway, triggering an inflammatory response and attracting immune cells to the tumor site." (PMID 40552293, 2025). "Considering the pro-tumor effects of AGK in tumor cells and its ability to suppress the mtDNA-induced cGAS-STING pathway in macrophages, targeting AGK may offer a novel and promising strategy for enhancing immunotherapy in the context of cancer treatments." (PMID 39816692, 2025). "The depletion of SAMHD1 by HSP90 inhibitor, alongside the triggering of the cGAS-STING pathway, may not only contribute to tumor cell apoptosis but also enhance the anti-tumor effect of ara-C in AML cells." (PMID 41392286, 2025). "In this study, we identified a compound, DHN, that specifically induces pyroptosis in tumor cells through the noncanonical cGAS/STING pathway." (PMID 40663398, 2025). "This suggests that ALDH1A3 not only plays a role in regulating cellular senescence but also participates in the regulation of SASP by influencing the cGAS–STING pathway, which may have a significant impact on the tumor microenvironment." (PMID 40227735, 2025). "There is evidence that tumors have the potential to suppress both cGAS and STING expression resulting in a hindered ability to detect DNA from the TME, which leads to a lowered immune response and ultimately continued growth of the tumor." (PMID 41157253, 2025). "In addition to its role in peptide encapsulation and protection, PEO-PC7A intrinsically acted as a stimulator of the interferon genes (STING) agonist, activating the cGAS-STING signaling pathway and remodeling the immunosuppressive tumor microenvironment." (PMID 41127047, 2025). "Emerging evidence suggests that modulation of the immune response through inhibition of these kinases, particularly via the cGAS-STING pathway and STAT1/STAT3 transcription factors, which activate a type I interferon response and upregulate PD-L1, contributes to anti-tumor immunity." (PMID 40977887, 2025). "The cGAS–STING pathway implicates host defense, inflammation, and tumor immunity." (PMID 39975542, 2025). "Additionally, genomic instability, a hallmark of many cancers, can lead to the release of DNA into the cytoplasm, activating inflammatory pathways like the cGAS/STING pathway, potentially enhancing the anti-tumor immune response." (PMID 40563651, 2025). "In a mouse model of LC, MOF‐CpG‐DMXAA significantly enhanced the innate immune response by synergistically activating the cGAS‐STING‐NF‐κB signaling pathway, achieving an 80% tumor clearance rate and completely inhibiting tumor recurrence, providing a novel strategy for solid tumor immunotherapy." (PMID 41201063, 2025).
tumor (continued). "Indeed, nuclear cGAS can disturb the formation of the PARP–Timeless complex, impede HR, diminish genomic stability, and promote tumor cell development." (PMID 40565309, 2025). "Following this, the platform adjusted the immune microenvironment of OS, with sequentially released manganese ions promoting DC maturation via the cGAS-STING pathway, enhancing antigen presentation and ultimately leading to tumor eradication through cellular immunity." (PMID 39936146, 2025). "For example, activation of cGAS-STING can be triggered by DNA-damaging therapies such as chemotherapy (cisplatin and doxorubicin) or radiotherapy, leading to the induction of an anti-tumor immune response." (PMID 41007722, 2025). "DNA sensing is a ubiquitous innate immune pathway in both immune and tumor cells, initiated when cyclic GMP-AMP synthase (cGAS) detects cytosolic DNA and produces 2′3′-cyclic GMP-AMP (2′3′-cGAMP), which activates STING to trigger TBK1/IRF3-dependent IFN-β and ISG expression." (PMID 41148213, 2025). "cGAS-STING activation can also promote tumor metastasis in cell-autonomous and non-cell-autonomous manners." (PMID 40052963, 2025). "Hence, the complex roles of the cGAS-STING pathway in tumors have been increasingly recognized, particularly in its dual functions of both promoting and suppressing tumor growth." (PMID 40075527, 2025). "Moreover, deletion of cGAS and STING reverses the anti-tumor effects of chemo-immunotherapy in small cell lung cancer." (PMID 40735041, 2025). "Previous studies have indicated that JMJD8 may interfere with the cGAS-STING pathway and the tumor microenvironment." (PMID 40761260, 2025). "Preclinical data suggest synergy between these classes via PARP-induced DNA damage, cGAS-STING activation, and enhanced tumor immunogenicity, which may be amplified by PD-1/PD-L1 blockade." (PMID 41541937, 2025). "This approach exploits the following two complementary mechanisms: PARP inhibitors create DNA damage and activate innate immune sensing via cGAS-STING, while PD-1/PD-L1 blockade restores T cell-mediated cytotoxicity in an increasingly inflamed tumor microenvironment." (PMID 41541937, 2025). "Importantly, 131I-Mn/SAE@M activated the cGAS-STING pathway, interfered with the lipid metabolic homeostasis of tumor cells, and induced ferroptosis, which is unraveled to take responsibility for the potentiated antitumor immunity." (PMID 40968370, 2025). "Notably, mitotic missegregation and chromosome fragments produced by genomic instability trigger the cGAS-STING pathway, promoting immunosurveillance and suppressing tumor progression." (PMID 40227811, 2025). "We found that PRMT5 inhibition in combination with the DNA‐damaging chemotherapeutic drug CPT‐11 induced a dMMR‐like state, thereby enhancing cGAS‐STING pathway activation and anti‐tumor immune reprogramming, ultimately increasing the sensitivity to ICIs treatment in MSS CRC." (PMID 40344511, 2025). "Amongst these actors, the cGAS-STING pathway, activated by CIN has been demonstrated to play a critical role in immunomodulation and possess long-term immunosuppressive tumor properties." (PMID 40227811, 2025). "ATR inhibition leads to the accumulation of cytosolic DNA fragments that activate the cyclic GMP-AMP synthase-stimulator of interferon genes (cGAS-STING) pathway, a key sensor of DNA damage that stimulates type I interferon signaling and promotes immune-mediated tumor clearance." (PMID 40869030, 2025). "Similarly, PRMT1 can suppress the cGAS–STING‐I type interferon pathway in GC, impede M1 macrophage polarization and CD8+ T cell recruitment triggered by dsDNA, and preserve the “cold tumor” phenotype." (PMID 41256732, 2025). "These augmented anti-tumor effects were not cancer cell intrinsic, but instead activated the cGAS/STING1 pathway and enhanced infiltration of tumor-killing immune cells." (PMID 40105196, 2025).
tumor (continued). "Interestingly, a recent study showed that CIN triggers the IL-6/STAT3 signaling pathway located downstream of cGAS-STING, and the blockage of IL-6 signaling impairs tumor growth in a TNBC model with high CIN." (PMID 40227811, 2025). "MtDNA that escapes into the cytosol activates the cGAS-STING pathway to initiate inflammatory responses, exhibiting dual roles in the tumor microenvironment: it can potentiate anti-tumor immunity while paradoxically fostering tumor progression under certain conditions." (PMID 41008599, 2025). "Acute DDR blockade—such as short-term PARP or ATR inhibition—induces rapid accumulation of cytosolic DNA, robust cGAS–STING activation, type I interferon release, and increased antigen presentation, thereby creating a transient window of heightened tumor immunogenicity." (PMID 41373427, 2025). "Acting as the cell’s central alarm system for misplaced DNA, the cGAS-STING pathway is a critical sentinel that can either rally the body’s immune defenses or, if hijacked, sound a false alarm that ultimately benefits the tumor." (PMID 41573551, 2025). "Moreover, the cGAS-STING signaling pathway interacts with Hippo/YAP signaling, significantly influencing tumor immunity and progression." (PMID 40673277, 2025). "CD80 surface expression, which was reduced in CD8+ T cells when tumors lacked cGAS, was unaltered in tumor-infiltrating T cells from Lrrc8c−/− mice." (PMID 41419196, 2025). "Additionally, engineered nano systems have been developed to activate the cGAS/STING pathway, effectively inhibiting tumor growth and recurrence by reversing immunosuppressive state within the tumor microenvironment." (PMID 40977697, 2025). "As the main target in immunotherapy, the cGAS-STING pathway could promote innate and specific immunity and exhibit anti-tumor effects." (PMID 40075527, 2025). "On the other hand, through rational design and functional modification, materials can possess multiple functions, such as simultaneously activating the cGAS-STING pathway, modulating the tumor microenvironment, and enhancing immune responses, to maximize the synergistic antitumor effect." (PMID 40567603, 2025). "As an emerging class of immunotherapeutic agents, oncolytic viruses (OV) induce ICD, promoting the release of DAMPs and activating innate immune pathways such as cGAS-STING, thereby transforming “cold” tumors into “hot” phenotypes and eliciting robust anti-tumor responses." (PMID 40977706, 2025). "Third, the Cu3P-induced cuproptosis effect not only increases the expression of PD-L1 in tumor cells and then sensitizes the ICB-mediated tumor therapy, but also activates the cGAS-STING pathway and realizes the cascade amplification of antitumor immune response." (PMID 41142419, 2025). "Interestingly, in vitro, irradiation of 4T1 carcinoma cells in the absence of the tumor stroma showed upregulation of ISGs, except Ifnb1, suggesting that the cGAS‐STING pathway may be variant in 4T1 cells and that tumor stromal cells play a critical role in RT‐activated immune responses." (PMID 40470716, 2025). "In combination therapy utilizing cGAS‐STING‐targeted nanovaccines and checkpoint inhibitors, the latter function by counteracting the immunosuppressive conditions within the tumor microenvironment, thus reinvigorating T‐cell functionality to effectively identify and eliminate cancer cells." (PMID 41476652, 2025). "For example, NR1D1 significantly increase the number of macrophages, dendritic cells and CD8+ T cells infiltrating in tumor tissues through activation of the cGAS-STING signaling pathway, thereby enhancing the anti-tumor immune effect and inhibiting breast cancer lung metastasis." (PMID 40166469, 2025). "Recent studies revealed that TH1902 could trigger the cGAS/STING pathway and potentiate anti-PD-L1 immune-mediated tumor cell killing in murine B16-F10 melanoma syngeneic tumor model." (PMID 39861694, 2025).
tumor (continued). "In general, BRCA-mutated cancers are characterized by genomic instability due to deficient DNA repair by homologous recombination, which promotes the generation of neoantigens, robust cGAS-STING signaling and increased number of tumor infiltrating lymphocytes, making it an attractive target for ICB." (PMID 40691137, 2025). "Moreover, shSTING significantly inhibited the IR-mediated activation of the cGAS–STING pathway, suppressed apoptosis and inhibited CD8+ T cell infiltration in the tumor microenvironment." (PMID 40355720, 2025). "IDH3α overexpression in cancers like uterine cervical cancer (UCC) and lung adenocarcinoma (LUAD) contributes to chemoimmunotherapy resistance by creating an acidic tumor microenvironment (TME) that impairs immune cell function, especially CD8+ T cells, and inhibits the cGAS–STING pathway." (PMID 39949780, 2025). "Additionally, MnSx activated the cGAS/STING pathway, which amplified the cellular autophagic response, further accelerating the tumor-killing effect." (PMID 39936146, 2025). "Anti-HER2 therapies (e.g., trastuzumab) may partially restore cGAS-STING pathway function, activating the tumor-killing activity of CD8+ T cells and NK cells." (PMID 40567603, 2025). "We observed lower baseline STING expression in HPV16-related OPSCC tumor cells compared to other models, yet its activator, cGAS, showed no such difference." (PMID 41401057, 2025). "The released self-DNA initiates the cGAS-STING signaling pathway, which may suppress tumor growth by exerting antiproliferative effects and inducing cell-autonomous death." (PMID 40362284, 2025). "Moreover, ATR–CHK1 blockade induces the accumulation of cytosolic double-stranded DNA and micronuclei, which in turn activate the cGAS/STING pathway, leading to type I interferon responses and a pro-inflammatory tumor microenvironment." (PMID 40869030, 2025). "Furthermore, elevated expression levels of CGAS and STING1 in tumor cells promoted their interaction with T cells, which is crucial for enhancing the efficacy of immunotherapy." (PMID 40735041, 2025). "Manganese (Mn), an essential trace mineral in the human body, plays a pivotal role in activating the host immune system via the cyclic guanosine monophosphate–adenosine monophosphate (GMP–AMP) synthase (cGAS)–stimulator of interferon genes (STING) pathway, enhancing anti-tumor immunotherapy." (PMID 39936146, 2025). "Radiotherapy can trigger the abscopal effect through immunogenic cell death, releasing tumor antigens and danger signals such as HMGB1 and calreticulin, which activate dendritic cells and prime cytotoxic CD8+ T cells via the cGAS–STING/type I interferon pathway." (PMID 41300968, 2025). "These fragments activate the cGAS-STING pathway, triggering pro-inflammatory cytokine release and recruiting immune cells, including CD8+ T cells, macrophages, and natural killer cells, to the tumor microenvironment." (PMID 39949780, 2025). "Furthermore, the combination of PRMT5i with CPT‐11 elicited a dMMR‐like state and activated cGAS‐STING signaling in a PMS2‐dependent manner, which subsequently enhanced CD8+ T cell‐mediated anti‐tumor immunity and increased sensitivity to αTIGIT treatment." (PMID 40344511, 2025). "In summary, PRMT1 is a central regulator of immune response, inflammation regulation, and tumor immune escape, achieved by methylating diverse nonhistone substrates and finely regulating key immune signaling pathways such as cGAS–STING, NF‐κB, and MHC‐II." (PMID 41256732, 2025). "This interplay between tumor-intrinsic and nonautonomous mechanisms highlights the dual roles of cGAS-STING in both reinforcing tumor progression and shaping the tumor microenvironment to support metastatic growth." (PMID 39949780, 2025).